IL13 (interleukin 13)
Diseases named in the same sentence as IL13 in open-access papers (continued):
Sharing a sentence is not in itself a finding about the gene and the disease.
liver fibrosis (136 papers, 2008 to 2026). "Elevated levels of IL-13 in chronic schistosomiasis patients with liver fibrosis are associated with disease progression." (PMID 40446079, 2025). "In a group of patients with advanced liver fibrosis, liver steatosis was linked with lower serum concentrations of IL-4, IL-5, IL-9, IL-10, IL-13 and IL-22." (PMID 39200991, 2024). "In patients with mild liver fibrosis, liver steatosis was associated with lower serum concentrations of IL-13 and IL-17F." (PMID 39200991, 2024). "A study on 611 patients with Schistosoma japonicum infection confirmed the association of Th2 cytokines, including IL-4 and IL-13, with liver fibrosis." (PMID 36982747, 2023). "Since IL-13 affects hepatic stellate cells, IL-13 inhibition would be associated with a reduction in hepatic fibrosis." (PMID 37629063, 2023). "Hepatic fibrosis is mainly caused by IL-13, which has been shown to play a major role in its development." (PMID 36743413, 2023). "In the context of S. japonicum, a single nucleotide polymorphism (rs1800925T) of the IL13 promoter has already been revealed with increased IL13 gene expression in the liver and an increased risk of pathological liver fibrosis." (PMID 37629063, 2023). "The association between IL-13 and a programmed death-ligand 2 polymorphism was predictive of advanced liver fibrosis." (PMID 37629063, 2023). "Higher levels of IL13 Ra1 in PSC-EVs were associated with severe liver fibrosis while lower levels of EV-IL13 Ra1 were associated to moderate liver fibrosis." (PMID 35194091, 2022). "IL-13 rs1800925T has been associated with a higher risk of pathological hepatic fibrosis in S. japonicum infected individuals." (PMID 34048465, 2021). "ILC2s are known to expand in response to IL-33 in liver fibrosis and are a major source of IL-13, which causes hepatic stellate cell activation independently of adaptive immunity (fibrosis is not attenuated in Rag deficient mice)." (PMID 32079296, 2020). "MMP‐12 expression has been linked to hepatic fibrosis through the attenuation of IL‐13‐dependent induction of MMP‐2, −9, and −13 in liver." (PMID 32951289, 2020). "Our previous results showed the association of IL-13 and tTG for the development of liver fibrosis after Sj infection." (PMID 31200771, 2019). "The IL-33/IL-13 pathway is associated with the immunopathological process of liver fibrosis, and hepatic group 2 innate lymphoid cells (ILC2s) have been identified as fibrogenic immune cells in the murine liver." (PMID 31888743, 2019). "Given that both IL-33/ST2 and tTG have been implicated in fibrosis through the release of IL-13, this study was undertaken to genetically validate the role of tTG in liver fibrosis during Sj infection and the relationship between tTG and IL-33/ST2." (PMID 31200771, 2019). "In the current study, low IL-10 levels were associated with moderate/severe hepatic fibrosis while IL-13 was raised in this group." (PMID 29610679, 2018). "The current findings are consistent with those from Brazil where a significant association between high IL-13 levels and severe hepatic fibrosis in S. mansoni infected individuals was documented." (PMID 29610679, 2018). "Among the Th2 cytokines involved in the pathogenesis of S. mansoni, IL-13 has been identified as a key profibrotic cytokine in the development of Schistosoma induced hepatic fibrosis, the main cause of morbidity and mortality in chronic S. mansoni disease." (PMID 29610679, 2018). "Our findings also confirmed that CsTPs initiated Th2-cell skewing immune responses to markedly elevate the production of IL-13 and IL-4 which are closely associated with the generation of liver fibrosis." (PMID 29505573, 2018). "Our current study also demonstrated the IL13 SNP rs1800925T allele is associated with increased risk of liver fibrosis." (PMID 26258681, 2015).
liver fibrosis (continued). "Our previous study demonstrated that HSC of Sj-infected-mice liver were activated and the extent of liver fibrosis gradually worsened from week 5 to week 12, and these changes were associated with tTG and IL-13 levels." (PMID 26199461, 2015). "In this study, we take an important step toward answering these questions by uncovering a novel connection among tTG, IL-13, and Sj-caused liver fibrosis." (PMID 25110399, 2014). "IL-13 has been implicated in both lung and liver fibrosis, though studies examining levels of IL-13 in UC and CD intestine have had contradictory results." (PMID 23300643, 2012). "Furthermore, CGA prevents liver fibrosis caused by schistosomiasis via altering the interleukin-13 (IL-13)/miR-21/Smad7 signaling relationship in the hepatic stellate LX2 cell line." (PMID 41142236, 2025). "In contrast, IL-13-associated loss of mucosal gut barrier function and IL-13-associated enhanced hepatic fibrosis may contribute to the progression of MASH." (PMID 37629063, 2023). "miRNAs such as miR-21 are elevated during hepatic fibrosis and studies that have shown the reduction of the latter due to the inhibition of the molecule by adeno-associated virus serotype 8 (rAAV8), which inhibits IL-13/SMAD and TGF-β1/Smad signaling pathways." (PMID 34281269, 2021). "Indeed, IL-13 expression levels have been associated with the severity of hepatic fibrosis in S. mansoni infection." (PMID 33737927, 2021). "High IL-13 is associated with the development of hepatic fibrosis and periportal fibrosis." (PMID 34048465, 2021). "In addition, an IL-13 promoter enhancing single nucleotide polymorphism (SNP), rs1800925, has been shown to strongly associate with a higher risk of pathological hepatic fibrosis in S. japonicum-infected individuals." (PMID 30546364, 2018). "In conclusion, IL13 functional polymorphism rs1800925T may increase the risk of liver fibrosis by S. japonicum by elevating IL-13 expression in the liver." (PMID 26258681, 2015). "In summary, we confirmed that tTG-regulated TGF-β1 and IL-13 were associated with liver fibrosis in mice after Sj-infection; thus, tTG might serve as a potent treatment target." (PMID 26199461, 2015). "Our previous report also confirmed that tTG is involved in the development of Sj infection-induced liver fibrosis in mice, and the mechanism may be associated with tTG-regulated IL-13 expression." (PMID 26199461, 2015). "Our previous research showed that tTG is involved in the development of Sj-infection-induced liver fibrosis in mice, and the underlying mechanism may be associated with tTG-regulated IL-13 expression." (PMID 26199461, 2015). "Our data showed the association of IL-13 and tTG with liver fibrosis." (PMID 25110399, 2014). "The complete interaction of ILC2s with eosinophils, M2s and Tregs in the context of liver fibrosis are not fully understood but since ILC2s are implicated as central players in hepatic fibrosis it is likely that eosinophils as well as M2 macrophages participate as sources of IL-13 and perhaps TGFβ." (PMID 32079296, 2020). "As IL-13 is considered the major pro-fibrotic mediator, we speculated that CsTPs-induced high level of IL-13 may contribute primarily to the generation and development of liver fibrosis caused by C. sinensis infection." (PMID 29505573, 2018). "But Th2 cytokines such as IL-4, IL-10 and IL-13 are associated with the aggravated pathological injuries and our previous study showed that the imbalanced Treg/Th17 may play a role in the formation of liver fibrosis." (PMID 28151995, 2017). "Because the presence of liver fibrosis differentiates the late-stage cases from chronic cases or healthy controls and IL13 SNP rs1800925 was associated with higher risk of liver fibrosis, we further tested whether IL-13 expression was enhanced in liver fibrosis tissue." (PMID 26258681, 2015).
liver fibrosis (continued). "Our study suggests, for the first time, a functional polymorphism in IL13 is associated with higher protein levels in fibrotic liver tissue resulting from S. japonicum infection These data implicate IL-13 in the development and progression of liver fibrosis in the context of S. japonicum infection." (PMID 26258681, 2015). "The Th2-derived cytokines IL-4 and IL-13 activate hepatic stellate cells, driving excessive extracellular matrix (ECM) deposition—a hallmark of hepatic fibrosis." (PMID 41154658, 2025). "IL-13 promotes liver fibrosis through two main mechanisms: I) IL-13 produced by Th2 clones polarizes macrophages toward the M2 phenotype." (PMID 40446079, 2025). "Despite the potential anti-inflammatory role of Th2 cells in MASLD, their involvement in liver fibrosis progression, particularly in the presence of IL-13, is evident." (PMID 40370443, 2025). "It has been shown that the IL-4/STAT6 and IL-13/STAT6 signaling pathways exacerbate the progression of metabolically induced liver fibrosis in mice on HFD." (PMID 41409600, 2025). "In fact, Il5−/− mice exhibit less hepatic fibrosis following parasite infection, while IL-13 appears to drive an alternative TGF-β–independent pro-fibrotic pathway in MASH." (PMID 41275524, 2025). "IL-33 promotes the recruitment of the second group of congenital lymphocytes (ILC2s) in the liver, and ILC2s secrete IL-13 to promote the development of liver fibrosis." (PMID 38105713, 2024). "Th2 cells are typically associated with anti-inflammatory effects; however, they can also contribute to the development of liver fibrosis, particularly through the actions of IL-13." (PMID 39148730, 2024). "In a subgroup of patients with advanced liver fibrosis, SLD was linked with lower serum concentrations of IL-4, IL-5, IL-9, IL-10, IL-13 and IL-22 and higher concentrations of HGH and VEGF." (PMID 39200991, 2024). "Further mechanisms suggest that IL-13 affects miR-21/Smad7 signaling, which in turn affects liver fibrosis." (PMID 38770001, 2024). "IL-13 promotes liver fibrosis formation by directly inducing the expression of liver fibrosis-related genes such as collagen and CTGF." (PMID 39735699, 2024). "In summary, although Th2 cells exert a protective function through the modulation of inflammation, they also intricately participate in the pathogenesis of NASH by promoting liver fibrosis via IL-13 signaling pathways." (PMID 39148730, 2024). "IL-33 induces M2-type polarization in macrophages and the release of IL-5 and IL-13 to promote liver fibrosis." (PMID 38105713, 2024). "IL-13 has been observed to promote hepatic fibrosis during the formation of liver fibrosis in Schistosoma-infected mice; Overexpression of IL-13 in the lungs induces marked subepithelial respiratory fibrosis in mice without any other inflammatory stimulus." (PMID 38879568, 2024). "Our results have shown significantly decreased levels of IL-13 in patients with steatosis, particularly those exhibiting advanced liver fibrosis, highlighting the importance of this pleiotropic cytokine in the pathogenesis of CHC as well." (PMID 39200991, 2024). "In a schistosome model of liver fibrosis, IL-13 inhibition led to granuloma formation and increased survival." (PMID 37629063, 2023). "In schistosomiasis, IL-13 has emerged as a central mediator of chronic-infection-induced liver fibrosis and portal hypertension, and IL-13 was identified as a primary mediator of liver fibrosis." (PMID 37629063, 2023). "As demonstrated in other models of liver fibrosis, IL-13 can be activated via the IL-33 pathway, implying that the liver fibrosis mechanisms during schistosomiasis are mainly driven by a balance between IL-33 and IL-13 instead of TGF-β." (PMID 37373379, 2023). "IL-13 has been suggested to contribute indirectly to HBV-related liver fibrogenesis by upregulating CCL11, which has a significant association with liver fibrosis." (PMID 36544761, 2022).
liver fibrosis (continued). "IL-33 promotes the recruitment of Group 2 innate lymphoid cells (ILC2s) in the liver, and secretion of IL-13 by ILC2s promotes the development of liver fibrosis." (PMID 36389166, 2022). "IL-13 has been referred to play a role in liver fibrosis, as a component of a T-helper type 2 inflammatory response and activates transforming growth factor 1 (TGF-β1)." (PMID 36544761, 2022). "The elevated expression of IL-33 is associated with the activation of IL-33 receptor (IL-33R) through ST2 signaling, leading to the increased production of IL-4 and IL-13 with the increase in liver fibrosis." (PMID 36271450, 2022). "Since IL-33 can promote Th2 response and increase the production of type 2 cytokines, such as IL-4, IL-5, and IL-13, which leads to extracellular matrix accumulation, administration of recombinant IL-33 to mice exaggerated liver fibrosis in NASH mice." (PMID 36032141, 2022). "In OB, interleukin-4 and interleukin-13 indicated via the IL-4R modulates adipose tissue lipolysis, insulin sensitivity, and liver fibrosis." (PMID 36314741, 2022). "IL-33 induces macrophage M2-type polarization and releases IL-5 and IL-13 to promote liver fibrosis." (PMID 36389166, 2022). "Meanwhile, IL4 and Il-13 enhance macrophage differentiation to M2 cells which promote the synthesis of liver collagen and subsequent hepatic fibrosis." (PMID 35576078, 2022). "Studies using the carbontetrachloride (CCl4)-induced liver fibrosis mouse model showed that ILC2s mediate liver fibrosis by producing the pro-fibrotic cytokine IL-13." (PMID 35203525, 2022). "Although the IL-33/IL13 axis clearly promotes liver fibrosis, the specific contribution of ILC2 and type 2 immune cells remains to be investigated." (PMID 33869241, 2021). "Cytokines IL-10 and IL-13 are considered as anti-inflammatory and upregulated in acute liver injury and liver fibrosis to prevent the damage." (PMID 33679236, 2021). "Type 2 immune response characterized by type 2 cytokines plays an important role in liver fibrosis as IL-4, IL-13, and TGF-β1 produced by macrophages can activate HSCs leading to liver fibrosis." (PMID 34733286, 2021). "Consequent research has also suggested the role of miRNAs in regulating hepatic fibrosis by activating HSCs via the downregulation of miR-203 thus increasing IL-33 expression, which stimulates IL-13 and consequent production of hepatic lymphoid cells." (PMID 34281269, 2021). "Th2 cytokines such as IL-4 and IL-13 promote hepatic stellate cell activation and accelerate the process of liver fibrosis." (PMID 34190168, 2021). "In patients with BA, the IL-33/IL-13 pathway was correlated with liver fibrosis progression, in which IL-33 is secreted and binds ST2 receptors on mast cells to release IL-13/TGF-β1, which mediate the process of fibrosis." (PMID 34858903, 2021). "The principal cytokine responsible for this is IL-13 and studies have shown failure to develop severe hepatic fibrosis in IL-13 knockout (KO), ineffective or neutralized mice." (PMID 34281269, 2021). "Interleukin-4 (IL-4) and IL-13 signaling via IL-4Rα regulates adipose tissue lipolysis, insulin sensitivity, and liver fibrosis in obesity." (PMID 34302121, 2021). "The Th2 cytokine IL-13 is involved in biliary epithelial injury and liver fibrosis in patients as well as in animal models." (PMID 32846954, 2020). "Recently, it has been demonstrated that IL-13 simultaneously and independently promoted hepatic fibrosis and the biliary reaction to progressive liver disease." (PMID 32846954, 2020). "TGF-β and IL-13 are well-documented as two important cytokines of liver fibrosis in mice infected with S. mansoni and S. japonicum, and IL-13 is the key driving liver fibrosis." (PMID 32611373, 2020). "Since it was observed that ECM deposition and thereby fibrogenesis were reduced in mice devoid of either IL-33- or IL-13-signalling, it was concluded that liver fibrosis was solely dependent on activated ILC2s." (PMID 30999584, 2019).
liver fibrosis (continued). "Tissue transglutaminase (tTG)-regulating IL-13 plays an important role in the pathogenesis of liver fibrosis resulting from Schistosoma japonicum (Sj) infection." (PMID 31200771, 2019). "In our previous studies, we have provided evidence that tTG regulates TGF-β1 of Sj origin and IL-13 of the host and documented the importance of tTG in liver fibrosis during Sj infection." (PMID 31200771, 2019). "Activated ILC2s expressed IL-13 that subsequently triggered trans-differentiation of HSCs into myofibroblasts that produced extra-cellular matrix (ECM)-components thereby promoting liver fibrosis." (PMID 30999584, 2019). "We recently reported that tTG-induced regulation of IL-13 plays an important role in the pathogenesis of liver fibrosis resulting from Sj infection." (PMID 31200771, 2019). "Corilagin reduces liver fibrosis induced by S. japonicum infection via reducing the expression of IL-13/STAT6 signal pathway-related molecules in alternative activated macrophages." (PMID 31886304, 2019). "Meanwhile, IL-13 can activate macrophages into M2-types, which promote synthesis of liver collagen and subsequent hepatic fibrosis." (PMID 31888743, 2019). "In this context, previous reports have shown that the IL-33/ILC2/IL-13 axis exacerbates liver fibrosis in mice, with circumstantial evidence of the activation of this axis in human cirrhosis." (PMID 31022195, 2019). "In conclusion, in mice and humans hepatic ILC2s are essentially involved in the pathogenesis of hepatic fibrosis by expressing IL-13." (PMID 30999584, 2019). "As in lung tissue, Th2 pro-fibrotic cytokines production such as IL-4, IL-5, and IL-13 are known to play a critical role in liver fibrosis." (PMID 30405626, 2018). "This trend gained further strength in animal-model-based study where a HMGB1 inhibitor was able to downregulate the production of the profibrotic cytokines IL4, IL-5, and IL-13 and significantly reverse (over 50%) liver fibrosis." (PMID 30546364, 2018). "In our study, IL-13 was significantly correlated with disease severity confirming earlier reports that this cytokine induces hepatic fibrosis." (PMID 29610679, 2018). "As a critical profibrotic cytokine found in various organs, including the liver, IL-13 is thought to be the key mediator of liver fibrosis in S. mansoni infections." (PMID 29703259, 2018). "Our findings also illustrated that CsTPs endowed host with the capacity to facilitate a Th2 cytokine production including IL-13 and IL-4 in vitro and vivo, thus possibly promoting the formation and development of liver fibrosis." (PMID 29505573, 2018). "Since GZR- or DIC-mediated inhibition of HMGB1 culminated in the downregulation of IL-13, a cytokine known to be involved in liver fibrosis regulation, we decided to investigate the role of HMGB1 in the pro-fibrotic processes of murine schistosomiasis." (PMID 30258438, 2018). "IL-4Rα-signaling involves both IL-4- and IL-13-mediated receptor engagement and the particular role of IL-13 was revealed to drive hepatic fibrosis." (PMID 30459767, 2018). "In accordance with the smaller granuloma size and less extensive hepatic fibrosis in group f/mf at week 19, lower serum cytokine levels of pro-fibrotic IL-4 and IL-13 were measured." (PMID 28542175, 2017). "IL-33 is pro-fibrogenic, as its hepatic expression is sufficient to drive severe liver fibrosis through ILC2-derived IL-13; which is further demonstrated by a strong reduction of experimentally-induced liver fibrosis in mice lacking IL-33." (PMID 28611297, 2017). "We planned to clarify the further mechanism of corilagin on egg-induced hepatic fibrosis with IL-13 knock-out mice in vivo." (PMID 29094025, 2017). "We have determined that CGA has an anti-liver fibrosis effect on schistosome-infected mice by suppressing the IL-13/miR-21/Smad7 signaling interactions and has an anti-inflammatory effect through the suppression of the TLR2/TLR9-Myd88 signaling pathways." (PMID 29311932, 2017).